LGALS3 (galectin 3)
Diseases named in the same sentence as LGALS3 in open-access papers (continued):
Sharing a sentence is not in itself a finding about the gene and the disease.
atrial fibrillation (continued). "So far, data about the impact of preexisting atrial fibrillation on galectin-3 plasma levels in the patients with acute coronary syndromes were not published." (PMID 29118378, 2017). "Galectin-3, the binding partner of LG3BP, is itself amyloidogenic, an inducer of fibrosis, and is a risk factor for a variety of diseases, including atrial fibrillation, something highly pertinent to this discussion." (PMID 39942772, 2025). "Univariate logistic regression showed that atrial fibrillation, CKD stages 1–3, LAVI < 39 mL/m2, E/e` < 17, hs-CRP < 6.1 mg/L, TNF-alpha < 3.7 ng/mL, NT-proBNP < 1540 pmol/mL, sST2 < 31 ng/mL, galectin-3 < 28 ng/mL, and irisin > 10.8 ng/mL were associated with improved LVEF in individuals with HF." (PMID 40299414, 2025). "H. pylori infection/MetS, by provoking pericyte dysfunction, hyperhomocysteinemia, galectin-3, atrial fibrillation, gut dysbiosis, and mast cell activation pathologies, may contribute to adverse pregnancy and neonatal outcomes." (PMID 38673633, 2024). "At the same time, the level of Galectin-3 in plasma is a biomarker related to inflammation and fibrosis, and its increase may be related to the development of cardiac diseases, especially atrial fibrillation and thrombosis." (PMID 39139162, 2024). "However, serum galectin-3 and non-paroxysmal atrial fibrillation were predictors in the final model." (PMID 35039576, 2022). "Among potential risk factors, non-paroxysmal patterns of atrial fibrillation and high serum galectin-3 levels were predictive for increased recurrence of atrial tachyarrhythmias." (PMID 35039576, 2022). "We assessed the clinical implications of serum galectin-3 in patients with atrial fibrillation." (PMID 35039576, 2022). "We presume that diastolic dysfunction may affect the serum galectin-3 level more than the degree of cardiac galectin-3 deposits does in patients with atrial fibrillation." (PMID 35039576, 2022). "In multivariable Cox regression analysis, non-paroxysmal atrial fibrillation (hazard ratio 6.8; 95% confidence interval 1.6–28.9) and higher galectin-3 levels (hazard ratio 1.3; 95% confidence interval 1.0–1.7) were associated with increased risk of recurrence." (PMID 35039576, 2022). "Interestingly, a higher recurrence rate of atrial fibrillation was confirmed in patients undergoing surgical ablation and having higher galectin-3 levels after the procedure." (PMID 35410028, 2022). "Galectin-3 expression levels are increased in patients with atrial fibrillation and, to some point, may be useful in the assessment of the treatment results." (PMID 33801193, 2021). "Galectin-3: a biochemical marker to detect paroxysmal atrial fibrillation?" (PMID 34550239, 2021). "Galectin-3 may be involved in atrial structural remodeling, which involves progressive fibrogenesis in atrial fibrillation patients." (PMID 32899694, 2020). "Galectin-3 is a biomarker of fibrosis, and, thus, may be involved in atrial remodeling in atrial fibrillation patients." (PMID 29587379, 2018). "Some studies have investigated the correlation between galectin-3 concentration and the occurrence of atrial fibrillation (AF)." (PMID 39451549, 2024). "Therefore, serum galectin-3 could be used as a biomarker for evaluation of the atrial remodeling severity and post-ablative prediction of recurrence in patients with atrial fibrillation." (PMID 35039576, 2022). "Galectin-3 is a biomarker of fibrosis and atrial remodeling, involved in the mechanisms of initiation and maintenance of atrial fibrillation (AF)." (PMID 27677964, 2016). "Galectin-3 modulates CD98 and TGF-β signaling, promoting atrial fibrosis and myofibroblast growth, which are critical factors in the development of atrial fibrillation." (PMID 39063659, 2024).
atrial fibrillation (continued). "The results of the study demonstrated that the levels of the new circulating markers of remodelling, such as galectin-3, MMP-9 and PIIINP (amino terminal peptide of type III procollagen) were significantly higher in patients with atrial fibrillation." (PMID 35053194, 2021). "Furthermore, galectin-3 enhances atrial fibrosis via CD98 signaling, facilitating atrial fibrillation development, a prevalent arrhythmia in diastolic dysfunction patients." (PMID 39063659, 2024). "Galectin-3 is involved in the remodeling of the left ventricle, but it also plays a significant role in the remodeling of the atria, both electrical and structural, leading to the occurrence of one of the most common heart rhythm disorders, atrial fibrillation (AF)." (PMID 39346100, 2024). "The relationship between high serum galectin-3 and atrial fibrillation is still not entirely settled." (PMID 37513890, 2023). "Assessment of baseline characteristics indicated that patients with recurrence had higher proportions of non-paroxysmal atrial fibrillation and higher levels of serum galectin-3 compared to patients without recurrence." (PMID 35039576, 2022). "The role of galectin-3 in the pathophysiology of atrial fibrillation has not been fully elucidated as yet." (PMID 35053194, 2021). "Among paired groups of patients who were sorted according to the type of atrial fibrillation or comorbidities, serum galectin-3 was higher in the diabetic group than in the non-diabetic group (9.52 ± 2.36 versus 7.07 ± 1.98, p = 0.003) but was not different in other paired groups." (PMID 35039576, 2022). "However, because atrial fibrillation is a progressive disease with structural remodeling of both the atrium and the ventricle, this would not change the clinical implication of serum galectin-3." (PMID 35039576, 2022). "The aim of this study was to determine the concentration of galectin-3, PINP and PIIINP in patients with metabolic syndrome (MS) and atrial fibrillation (AF) with an assessment of the relationship with severity of left atrium fibrosis." (PMID 32784491, 2020). "In MetS patients who also had atrial fibrillation, significantly higher serum concentrations of galectin-3 were observed than in MetS patients without AF, leading researchers to suggest galectin-3 as a screening and prognostic marker for AF." (PMID 41590667, 2026). "In addition, it has been demonstrated that galectin-3 plasma concentrations are significantly higher in patients with preexisting atrial fibrillation (AF) compared with patients without AF." (PMID 35208606, 2022).
type 2 diabetes (62 papers, 2012 to 2026). "Galectin-3 has been shown to be involved in different diseases associated with chronic inflammation, cancer, and type 2 diabetes." (PMID 37571403, 2023). "Our analysis of the transcriptional response of the endothelium to an in vivo model of type II diabetes in galectin-3 deficient vs. wild-type mice has revealed differential responses in both aortic and skeletal muscle tissues." (PMID 26047815, 2015). "Based on this hypothesis, galectin-3 was also found to be independently associated with progressive renal disease in type 2 diabetes." (PMID 31080833, 2019). "Recent evidence also showed that extracellular Galectin-3 impaired glucose-stimulated insulin secretion in pancreatic β cells in type 2 diabetes (T2D) mouse models." (PMID 41477833, 2026). "Metformin, a drug commonly used for the treatment of patients with type 2 diabetes, reduced galectin-3 levels in adipocytes and monocytes and correlated with reduced serum galectin-3 levels." (PMID 40649879, 2025). "The Dallas Heart Study indicated a link between galectin-3 levels and both the occurrence and development of type 2 diabetes (T2DM), as well as various fat compartments." (PMID 39129285, 2025). "Future studies should focus on the delivery of galectin-3 in delayed healing models such as the db/db murine model of type II diabetes, which shows impaired re-epithelialization." (PMID 39451336, 2024). "While the role of galectin 3 expressed in islet-invading immune cells in both type-1 and type-2 diabetes has been studied, the importance of the expression of this molecule on the target pancreatic β cells has not been defined." (PMID 32117058, 2020). "On the other hand, galectin-3 levels correlated positively with insulin sensitivity and negatively with HbA1c levels in patients with type 2 diabetes." (PMID 26770660, 2016). "In light of our preliminary findings, we suspected that galectin-3 is involved in the endothelial dysfunction that leads to the vascular complications of type II diabetes." (PMID 26047815, 2015). "We measured serum galectin-3 levels in type 2 diabetes patients, and performed a glucose clamp method and a meal tolerance test (MTT) to evaluate insulin resistance and beta cell function." (PMID 25302080, 2014). "Indeed, systemic galectin-3 levels were found to be increased in type 2 diabetes, MAFLD, and infectious and autoimmune diseases and cancers." (PMID 40649879, 2025). "There is also evidence that galectin 3 plays a role in both type-1 and type-2 diabetes." (PMID 32117058, 2020). "Moreover, galectin-3 levels are higher in subjects with type 2 diabetes and have been suggested to have a role from prediabetes to type 2 diabetes." (PMID 29327139, 2018). "Thus, we sought to determine the role of galectin-3 in the vascular pathology and metabolic derangement observed in type II diabetes." (PMID 26047815, 2015). "Further investigations are needed because the pathophysiology of type 2 diabetes patients may be different from that of galectin-3 knockout mice." (PMID 25302080, 2014). "We consider that galectin-3 is associated with adiponectin rather than inflammation in patients with type 2 diabetes." (PMID 25302080, 2014). "Also, there is evidence that galectin 3 plays a role in both type-1 and type-2 diabetes." (PMID 32117058, 2020). "In conclusion, we provide direct evidence that expression of galectin 3 facilitates β-cell damage induced by cytokines and NEFA, therefore promoting type-2 diabetes." (PMID 32117058, 2020). "For instance, the sodium–glucose cotransporter 2 inhibitor empagliflozin, which is also used for the treatment of type 2 diabetes, did not change serum galectin-3 levels within 20 weeks of therapy." (PMID 40649879, 2025). "Moreover, both our study and previous research have reported significantly elevated galectin-3 (Gal-3) levels in patients with type 2 diabetes (T2D) compared to individuals without T2D." (PMID 40868983, 2025).
pancreatic cancer (60 papers, 2010 to 2025). "Although imaging studies (CT, MRI, etc.)and pathological analysis have become essential diagnostic tools for pancreatic cancer, recent research has increasingly recognized the potential of galectin-3 (Gal-3) as an effective early diagnostic molecular target." (PMID 40600063, 2025). "Based on the prognostic associations observed in pancreatic cancer, we next examined LGALS3 expression in pancreatic ductal adenocarcinoma (PDAC) at both transcriptomic and proteomic level." (PMID 41153387, 2025). "Galectin-3 (Gal-3) is a promising candidate for utilisation as a diagnostic biomarker in early-stage pancreatic cancer." (PMID 37915694, 2023). "Although galectin-3 exhibited some diagnostic value in patients with pancreatic cancer in this meta-analysis, clinical application prospects remain to be validated." (PMID 31832021, 2019). "In pancreatic cancer, this is linked to Akt-regulation by galectin-3, which in turn modulates GSK-3β phosphorylation and β-catenin degradation by suppression of the β-catenin/Wnt signaling pathway." (PMID 21958686, 2011). "RN1 is a polysaccharide isolated from flowers of Panax pseudo-ginsieng, which binds and downregulates galectin-3-associated signaling pathways, thereby reducing the proliferation rate of pancreatic cancer cells and the growth of patient-derived xenografts both in vitro and in vivo conditions." (PMID 36873388, 2023). "Some studies have proposed elevated circulating expression of galectin-3 as a potential biomarker for pancreatic cancer, and combined determination of galectin-3, CA19-9, and CA125 provided complementary diagnostic value for pancreatic cancer with a diagnostic sensitivity of 97.5%." (PMID 31832021, 2019). "Gal-3 is encoded by LGALS3 which is up-regulated in pancreatic cancer." (PMID 28262838, 2017). "Overcoming the stromal and immunosuppressive barriers in pancreatic cancer remains critical for translating galectin-3-directed strategies into clinical benefits." (PMID 40600063, 2025). "Continuous monitoring of tumor growth revealed that HPSC/LGALS3 overexpression accelerated pancreatic tumor growth, counteracting the effects of gemcitabine therapy." (PMID 40600063, 2025). "The same is the case for Galectin-3 (LGALS3) and Galectin-4 (LGALS4), associated with gastro-intestinal cancers, which are downregulated in colorectal (COREAD) but upregulated in pancreatic cancer (PAAD)." (PMID 38384845, 2024). "Strongly detected in pancreatic tumors, galectin-3 stimulates PSCs via integrin signaling, promoting the development of malignancies and immune control." (PMID 38202898, 2023). "Examples of clinical correlation between PDCA prognosis and these genes include: 1) A correlation was noted between the overall survival of the pancreatic cancer patients with plasma Galectin-3 levels (n = 21)." (PMID 37910468, 2023). "Galectin-3 also regulates pancreatic cancer metastasis through the activation of RAS–ERK/AKT and Rel-A signaling pathways, thereby increasing cell migration, and survival." (PMID 36873388, 2023). "In summation, while Galectin-3 heralds a promising horizon in pancreatic cancer diagnostics and prognostics, rigorous studies are imperative to delineate its definitive clinical utility." (PMID 37892182, 2023). "In the arena of pancreatic cancer biomarkers, Galectin-3 (Gal-3) stands out as a molecule of considerable significance." (PMID 37892182, 2023). "In contrast to galectin-1, the galectin-3 helps pancreatic tumor cells to participate in immune evasion mainly by interacting with the immune cells." (PMID 36428567, 2022). "Cervical cancer-derived HeLa, glioma-derived NCH125 and pancreatic carcinoma-derived BxPC3 cell lines were transfected with siRNAs targeting LGALS1 or LGALS3, or a scrambled siRNA." (PMID 35632759, 2022). "Given the co-occurrence of mutant KRAS with high HIF-1α and high galectin-3 levels in pancreatic cancer, our results suggest an application of Hsp90 inhibitors in this cancer type." (PMID 33672199, 2021).
pancreatic cancer (continued). "A recent study has shown that galectin-3 mediates tumor cell-stromal interactions in pancreatic cancer." (PMID 33255941, 2020). "In conclusion, Galectin-3 appears to reprogram selectively the translatome of pancreatic cancer cells in basal conditions through the control of S6RP and 4EBP1 activity." (PMID 32398681, 2020). "Meanwhile, a study has demonstrated that silencing galectin-3 can inhibit the migration and invasion of pancreatic cancer cells by down-regulating the level of Akt phosphorylation and GSK-3β protein." (PMID 30996686, 2019). "With respect to diagnostic value in pancreatic cancer, our meta-analysis suggested that the pooled DOR of galectin-3 was 5.93, but the 95% CI was 0.96–36.72, indicating an unsatisfactory diagnostic accuracy and substantial heterogeneity." (PMID 31832021, 2019). "Overexpressed galectin-3 in pancreatic cancer cells induced cell proliferation and invasion by activating Ras signaling." (PMID 31832021, 2019). "Several studies have indicated that Gal-3 mRNA is up-regulated in pancreatic tumor tissues compared to control tissues, and transient suppression of galectin-3 has been reported to induce pancreatic cancer cell migration and invasion." (PMID 22900040, 2012). "Using orthotopic implantation into the pancreatic bed, a model which better recapitulates in vivo pancreatic tumor growth, we have clearly demonstrated an effect of galectin-3 on pancreatic tumor growth." (PMID 22900040, 2012). "Galectin-3 (Gal-3), a member of the animal lectin family, is up-regulated in many tumors including pancreatic cancer." (PMID 22900040, 2012). "Our results confirm that galectin-3 is upregulated at the mRNA level in pancreatic cancer and strongly expressed in the majority of pancreatic cancer cell lines." (PMID 21698183, 2011). "Northern blotting and Western blotting analysis showed significantly higher galectin-1 and galectin-3 mRNA and protein levels in pancreatic cancer samples compared to normal controls." (PMID 23658855, 2010). "Taken together the expression pattern of galectin-1 and galectin-3 in pancreatic cancer tissues indicates that these proteins can be useful biomarkers in this type of cancer." (PMID 23658855, 2010). "This could be attributed to the presence of identical surface adhesion molecules, such as N-cadherin and galectin-3, on the surfaces of different pancreatic cancer cell lines." (PMID 40664640, 2025). "Galectin-3 (Gal-3) is a histologic marker of pancreatic cancer and a potential therapeutic target." (PMID 41295391, 2025). "The increased expression of the β3 integrin has been implicated in drug resistance, including resistance to erlotinib and lapatinib in lung cancer and to linsitinib in pancreatic cancer, through interactions with galectin-3 and the activation of KRAS, RELB, and the NF-ΚB pathway." (PMID 39201327, 2024). "One type of cancer that shows higher expression of galectin-3 is pancreatic cancer." (PMID 38202898, 2023). "By assessing its expression levels or detecting specific alterations, galectin-3 (Gal-3) could provide valuable insights into the presence and progression of pancreatic cancer, enabling early detection and intervention." (PMID 37915694, 2023). "However, some groups have reported that serum galectin-3 is higher in cases with pancreatic carcinoma than in benign pancreatic diseases and healthy subjects, which has also been observed in heart and kidney diseases." (PMID 38139416, 2023). "Since phosphorylation of both S6RP and 4EBP favours mRNA translation initiation, Galectin-3 inhibitory effect may induce a blockage of mRNA translation in pancreatic cancer cells in usual culture conditions (with FCS)." (PMID 32398681, 2020). "For that purpose, we used two models deriving from the human pancreatic cancer cell line T3M-4, control Sc cells expressing high levels of Galectin-3 and a representative mutant clone (Sh1 called Sh cells thereafter) where Galectin-3 expression was stably knocked-down by shRNA." (PMID 32398681, 2020).